TTL (tubulin tyrosine ligase)
Description:
Catalyzes the post-translational addition of a tyrosine to the C-terminal end of detyrosinated alpha-tubulin.
Synonyms: MGC46235
Tractability: Small molecule: a structure with a bound ligand is known; it belongs to a druggable protein family. PROTAC: ubiquitination databases record sites on it; its protein half-life has been measured; a small molecule that binds it is known.
Target class: Enzyme; Ligase
Gene: Protein-coding gene on chromosome 2 (112,482,113 to 112,541,739, forward strand). Ensembl gene ENSG00000114999.
Subcellular location (Human Protein Atlas): Vesicles; Nucleoplasm
Pathways (Reactome):
Metabolism of proteins: Carboxyterminal post-translational modifications of tubulin
Gene Ontology:
Molecular function: tubulin-tyrosine ligase activity
Biological process: positive regulation of mitotic cell cycle; post-translational protein modification; regulation of metaphase plate congression; microtubule cytoskeleton organization
Cellular component: spindle microtubule; microtubule
Genetic constraint (gnomAD): Loss-of-function variants: 10 observed, 40.09 expected, observed/expected ratio (o/e) 0.25, 90% interval 0.15 to 0.42. The upper end of that interval is the gene's LOEUF score, 0.42, which puts it in group 1 of 6, group 1 being the genes least tolerant of losing a copy. Missense variants: 363 observed, 468.59 expected, observed/expected ratio (o/e) 0.77, 90% interval 0.71 to 0.85. Synonymous variants: 175 observed, 180.63 expected, observed/expected ratio (o/e) 0.97, 90% interval 0.86 to 1.1.
Homologues: Orthologues: chimpanzee TTL (100% identical), rat Ttl (95% identical), guinea pig TTL (95% identical), mouse Ttl (95% identical), rabbit TTL (95% identical), dog TTL (88% identical), tropical clawed frog ttl (81% identical), zebrafish ttl (76% identical).
Diseases named in the same sentence as TTL in open-access papers:
TTL is named in the same sentence as 24 diseases in open-access papers, as found by Europe PMC text mining. Sharing a sentence is not in itself a finding about the gene and the disease. The quoted sentences say what the papers report.
Alzheimer disease (3 papers, 2021 to 2022). A progressive, neurodegenerative disease characterized by loss of function and death of nerve cells in several areas of the brain leading to loss of cognitive function such as memory and language. "The finding that the knock-in of the Alzheimer’s disease-linked London mutation in APP in in vitro differentiated human neurons also resulted in a drop in TTL compared to isogenic controls strongly supports a causal relationship between TTL loss and familial Alzheimer’s disease." (PMID 35148384, 2022). "In mice hemizygous for TTL (TTL±), reduced TTL expression, leads to a significant change in the detyrosinated/tyrosinated tubulin ratio, resulting in deficiencies in synaptic plasticity and memory; moreover, a reduced TTL level is characteristic for Alzheimer’s Disease." (PMID 34395449, 2021). "We analysed TTL levels and the different α-tubulin forms in protein extracts prepared from these four brain regions of Alzheimer’s disease patients and controls." (PMID 35148384, 2022). "Altogether, these results indicate that in Alzheimer’s disease, a global TTL impairment is present from an early stage of the neurodegeneration process and is associated with increased amounts of non-tyrosinated tubulin." (PMID 35148384, 2022). "We found that 2 days of chronic 100 nM oAβ exposure resulted in a 25.77 ± 5.23% reduction in TTL content, similar to what we observed in sporadic and familial Alzheimer’s disease samples." (PMID 35148384, 2022). "In this study, we identify a role for the retyrosination of α-tubulin by TTL activity in the maintenance of synaptic function and Alzheimer disease-related synaptic dysfunction." (PMID 35148384, 2022). "Interestingly, we recently observed that in Alzheimer’s disease (AD), TTL levels drop, driving MTs towards accumulating detyrosinated and Δ2 tubulin, markers of MT longevity and inhibitors of synaptic plasticity by reducing the frequency of tyrosinated MT invasion into dendritic spines." (PMID 36092705, 2022). "We examined whether TTL depletion was a bona fide feature of neurodegenerative disease and found that TTL was downregulated in both sporadic and familial Alzheimer disease, and that abnormally high levels of detyrosinated and Δ2 tubulins accumulated in brain samples of Alzheimer’s disease patients." (PMID 35148384, 2022).
Anxiety (2 papers, 2022 to 2024). Intense feelings of nervousness, tension, or panic often arise in response to interpersonal stresses. "Conditional TTL-KO in the forebrain leads to viable and fertile mice that have deficits in spatial learning and increased anxiety." (PMID 38525600, 2024).
familial Alzheimer disease (2 papers, 2022 to 2024). A degenerative disease of the brain that causes gradual loss of memory, judgment, and the ability to function socially. "We further report decreased TTL expression in sporadic and familial Alzheimer’s disease, and reduced microtubule dynamics in human neurons harbouring the familial APP-V717I mutation." (PMID 35148384, 2022). "While the molecular factors associated with the resistance of dynamic microtubules-invaded spines remain to be identified, our results indicate that TTL activators may be beneficial to restore circuit integrity in sporadic and familial Alzheimer’s disease." (PMID 35148384, 2022).
astrocytoma (1 paper, 2017). "Moreover, high expression of 7 of the high-malignant genes (C7ORF46, DUSP4, HS3ST3B1, ODZ1, TTL, VAV3, ZDHHC23) or low expression of 4 of the low-malignant genes (AKR1C3, ARHGEF10L, SMAD7, ST3GAL6) was associated with a lower progression free survival probability of grade III astrocytoma patients." (PMID 29152145, 2017).
Ataxia (1 paper, 2022). Ataxia refers to impaired coordination of voluntary muscle movement. "A crucial role during early development was suggested by our previous results in TTL-null mice that died within 24 h of birth with respiratory problems, ataxia, and severely altered neuronal morphologies." (PMID 36340693, 2022).
cardiac hypertrophy (1 paper, 2025). "Taken together, these data suggest that TTL p.G219S showed reduced activity, resulting in increased detyrosinated α-tubulin, consequently leading to oxidative stress culminating in cardiac hypertrophy." (PMID 40779454, 2025). "This mutation results in reduced TTL activity, leading to the accumulation of detyrosinated MTs and oxidative stress in patient-specific and CRISPR gene-edited iPSC-derived CMs, resulting in cardiac hypertrophy." (PMID 40779454, 2025).
cognitive deficits (1 paper, 2022). "The results presented so far showed that tyrosination of α-tubulin in the neocortex and hippocampus during development is important for network formation and that forebrain-specific deletion of TTL, therefore, leads to cognitive deficits and impaired synaptic plasticity." (PMID 36340693, 2022).
colon carcinoma (1 paper, 2017). "To investigate whether TTL is relevant in human tumors besides neuroblastoma, we examined TTL expression levels in human colon carcinoma and hepatocarcinoma tissues." (PMID 29228606, 2017). "Interestingly, decreased expression of TTL in tumor stromal cells also correlated with poor outcome in human colon carcinoma." (PMID 29228606, 2017).
colon tumors (1 paper, 2017). "Strikingly, low TTL expression in tissues of human colon cancer or hepatocarcinoma correlated with poor prognosis." (PMID 29228606, 2017). "Underlining this, TTL-mRNA levels in colon tumor tissues were significantly lower than that in non-malignant colon tissues." (PMID 29228606, 2017). "Although TTL levels did not correlate with size or metastasis of colon tumors, the average TTL levels in T4-stage tumor tissues was significantly lower than that in T3 stage." (PMID 29228606, 2017).
cyst (1 paper, 2022). A sac-like closed membranous structure that may be empty or contain fluid or amorphous material. "It thus seems plausible that the dramatic shortening of primary cilia observed in TTL-overexpressing MDCK cells alters epithelial differentiation and disrupts the coordinated sequence of events in 3D cyst formation." (PMID 35903547, 2022).
Duchenne muscular dystrophy (1 paper, 2023). Duchenne muscular dystrophy (DMD) is a neuromuscular disease characterized by rapidly progressive muscle weakness and wasting due to degeneration of skeletal, smooth and cardiac muscle. "In contrast, deregulation of these tubulin modifications was found in diseased muscles and overexpression of tubulin tyrosine ligase was used to attenuate contraction-induced injuries in a Duchenne muscular dystrophy mouse model and to improve the contractile kinetics in cardiomyocytes." (PMID 37178194, 2023).
tumor (11 papers, 2012 to 2021). "The expression pattern in tumor tissues is thereby linked to tumor aggressiveness with a favorable prognosis if TTL expression is high." (PMID 33614664, 2021). "Expression of TTL in general affects cell fate and there is a widespread loss of TTL activity during tumor growth in situ." (PMID 33614664, 2021). "This is consistent with the association between α-tubulin detyrosination and tumor aggressiveness, as well as with the frequent downregulation of TTL and consequent upregulation of α-tubulin detyrosination in several cancers." (PMID 33114575, 2020). "The most studied gene was tubulin tyrosine ligase: its downregulation in tumor-associated fibroblasts promoted TS/A tumor growth." (PMID 31783695, 2019). "Thus, TTL loss and the resulting tubulin detyrosination confer selective advantage to cancer cells during tumor growth." (PMID 23750272, 2013). "Conversely, down-regulated TTL expression in fibroblasts promotes tubulin detyrosination and tumor growth in mice." (PMID 33614664, 2021). "We successfully discovered 20 tumor-associated candidate genes and subsequently confirmed Ttl, the gene for tubulin tyrosine ligase as tumor-suppressor gene in TAFs within different mouse tumor models." (PMID 29228606, 2017). "TTL expression was found to be suppressed during tumor growth in mice, as well as during epithelial-to-mesenchymal transition in human mammary epithelial cells in vitro, implicating the tubulin tyrosination cycle in both tumor propagation and metastasis." (PMID 28218637, 2017). "For example, TTL loss, which results in the accumulation of Glu-tubulin, confers a selective advantage to cancer cells during tumor growth, and TTL suppression in mice leads to a lethal disorganization of the neuronal circuits." (PMID 27466378, 2016). "In tumour cells, however, the abundance of tyrosinated tubulin is decreased, and suppression of TTL activity promotes tumour aggressiveness." (PMID 25779700, 2015). "We have recently reported that epithelial-to-mesenchymal transition (EMT) promotes α-tubulin detyrosination by downregulating expression of TTL and that detyrosinated tubulin accumulates at invasive tumor fronts in patient samples." (PMID 24028602, 2013). "We demonstrated that down-regulated TTL expression in TAFs indeed promoted tumor growth in mice." (PMID 29228606, 2017). "In general, little is known about either modifying enzymes or the biological functions of these modifications, although the suppression of tubulin tyrosine ligase and subsequent accumulation of detyrosinated tubulin favors tumor growth in animal models and human cancers." (PMID 22363525, 2012). "Likewise, the induction of EMT also correlated with the downregulation of TTL and the consequent increase of tubulin detyrosination during tumor development, thus pointing to the possible involvement of these tubulin PTMs and associated enzymes in cell transformation." (PMID 33114575, 2020). "In addition to its implications for chemoresistance, research has shown that increased detyrosinated tubulin is associated with poor cancer prognosis and may arise from suppressed TTL activity during tumor growth which prevents re-tyrosination." (PMID 24028602, 2013). "Downregulation of TTL and increased α-tubulin detyrosination were reported during the epithelial–mesenchymal transition (EMT) that occurs during tumor invasion in prostate cancer cells, in aggressive subtypes of breast cancer cells, and in primary neuroblastomas with poor prognosis." (PMID 32823874, 2020). "In colon, TTL was highly expressed in the non-glandular stromal cells of non-malignant areas, but drastically decreased in the TAF-like stromal cells within tumor areas." (PMID 29228606, 2017).
cancer (7 papers, 2012 to 2023). A tumor composed of atypical neoplastic, often pleomorphic cells that invade other tissues. "Tubulin detyrosination, which results from the suppression of tubulin tyrosine ligase and the resulting unbalanced activity of tubulin-carboxypeptidase, apparently represents a strong selective advantage for cancer cells and has been linked to poor prognosis in BC." (PMID 37046635, 2023). "Interestingly, suppression of TTL has been associated with poor prognosis in several cancers." (PMID 24028602, 2013). "Six genes (PDXDC1, ATF7IP2, LIN7C JTB, TTL, DVL2), which regulate the ERG signal transduction pathways, were retained in 4 out of 9 LT patients, were significantly involved in transcriptional mis-regulation in cancer (multiple testing adjusted p-value = 0.025)." (PMID 35773268, 2022).
infection (3 papers, 2022 to 2025). The state of being infected such as from the introduction of a foreign agent such as serum, vaccine, antigenic substance or organism. "It is therefore possible that viral-encoded tubulin tyrosine ligase plays a role in viral trafficking and egress during infection." (PMID 39932282, 2025). "In hippocampal rat neurons, after 4 days of infection with shRNA against TTL, a time point at which TTL levels begin to drop but before spine density starts to decline, microtubule entries into spines significantly decreased." (PMID 35148384, 2022). "In contrast, TTL overexpression facilitated the accumulation of a larger pool (mean=75±0.6% at 4 h) of AAV2 near the nucleus in comparison to the untreated or GFP vector controls with AAV2 infection." (PMID 41140178, 2025).
cardiac diseases (1 paper, 2018). "Many of the predicted DCM functional genes were recently shown experimentally to be mechanistically linked to cardiac diseases; notably, the TTL gene, which was very recently shown to be directly involved in microtubule buckling during cardiac contraction." (PMID 29311597, 2018).
TTL also shares sentences with these, for which no sentence is quoted: heart failure (2 papers); alcohol dependence (1); breast carcinoma (1); fibrosarcoma (1); memory impairment (1); neuroblastoma (1); neurodegenerative disease (1); prostate tumors (1); tauopathy (1).